CHD9NB (CHD9 neighbor)
Synonyms: PR-lncRNA-1
Safety:
Unwanted effects reported when the protein is acted on. In parentheses: how it was acted on, where the effect was seen, and who reports it.
Anemia (source: ClinPGx)
anemia and neutropenia (source: ClinPGx)
Neutropenia (source: ClinPGx)
Gene: Protein-coding gene on chromosome 16 (53,035,690 to 53,052,897, reverse strand). Ensembl gene ENSG00000277639.
Homologues: Orthologues: pig CHD9NB (71% identical), mouse Gm19935 (60% identical).